CXCL12 (C-X-C motif chemokine ligand 12)
Diseases named in the same sentence as CXCL12 in open-access papers (continued):
Sharing a sentence is not in itself a finding about the gene and the disease.
myeloma (continued). "Because CXCL12/CXCR4/CXCR7chemokine axis activation regulates the pattern of tumor growth and metastatic spread to organs expressing high levels of CXCL12, NOX-A12 was expected to be useful in the treatment of several types of cancers, including multiple myeloma, lung, colorectal and brain cancers." (PMID 29301363, 2018). "Considering the key role of CXCL12 in the localization of NK cells in BM, subversion of the CXCR4/CXCL12 axis has been hypothesized to represent a mechanism of immune evasion from NK-mediated immune surveillance in neuroblastoma and multiple myeloma." (PMID 27766097, 2016). "To target the CXCR4/CXCL12 axis, we used the CXCR4 antagonist Motixafortide (MTF, BL‐8040), which is Food and Drug Administration (FDA)‐approved as a hematopoietic stem cell mobilizer in multiple myeloma, and tested whether combining MTF with CAR T cells potentiates cytotoxicity in our 3D model." (PMID 41368078, 2025). "CXCL12 is expressed by BMPCs (median = 219 normalized counts), but its expression levels are significantly lower from monoclonal gammopathy of undetermined significance (MGUS) to relapsed multiple myeloma (MMR; median = 9 normalized counts in MMR and absent expression in most HMCL)." (PMID 38598843, 2024).
myocardial infarction (101 papers, 2007 to 2025). Gross necrosis of the myocardium, as a result of interruption of the blood supply to the area, as in coronary thrombosis. "Genome-wide association studies of coronary artery disease and myocardial infarction have identified CXCL12 as a potential locus for AS." (PMID 38475787, 2024). "Human genome-wide association studies even have identified novel loci downstream of the CXCL12 gene locus associated with coronary artery disease and myocardial infarction." (PMID 34072818, 2021). "Direct injection of CXCL12, for example, reduced myocardial infarct size after ischemia, which was associated with increased neo-angiogenesis." (PMID 26257740, 2015). "Indeed, the in vivo administration of CXCL12 leads to a decrease in myocardial infarct size associated with signaling through the anti-apoptotic kinases ERK 1/2 and AKT in cardiac cells." (PMID 26347749, 2015). "This review aims to provide insight into the current concept of the CXCL12/CXCR4 axis in myocardial infarction (MI) and its underlying pathologies such as atherosclerosis and injury-induced vascular restenosis." (PMID 24966838, 2014). "Some are anti-atherosclerotic, such as Cxcl12, which plays a protective role after myocardial infarction, and Rbp7, which helps to increase nitric oxide bioavailability." (PMID 36910156, 2023). "One study identified the CXCR4—CXCL12 axis as necessary for early postnatal collateral formation in response to myocardial infarction." (PMID 35391845, 2022). "CXCL12 transgenic overexpressing (Tg) rats promoted inflammation and fibrosis after the induction of myocardial infarction." (PMID 35668739, 2021). "The chemokine receptor CXCR4 and its ligand CXCL12 have been shown to be a possible imaging and therapeutic target after myocardial infarction (MI)." (PMID 32676914, 2021). "In the ischaemia-reperfusion model, therapeutic CXCL12 2 hours in advance reduced the myocardial infarction area in mice." (PMID 35668739, 2021). "On the one hand, a great deal of evidence suggests an increase in plasma CXCL12 in patients with myocardial infarction." (PMID 35668739, 2021). "An increase in C-X-C Motif Chemokine Ligand 12 (CXCL12) has been shown in CKD patients and associated with left ventricular hypertrophy, hypertension, and CV events such as myocardial infarction." (PMID 34501251, 2021). "Using the regenerative properties of CXCL12 has been envisioned to be applicable in myocardial infarction and arterial injury." (PMID 25152735, 2014). "CXCL12 is a chemokine that has been shown to mediate the recruitment and homing of endothelial progenitor cells and promote angiogenesis in an experimental model of myocardial infarction and hind limb ischemia." (PMID 37817190, 2023). "One dose of CXCL12 at the time of adult myocardial infarction stimulated collateral growth." (PMID 35391845, 2022). "In adult mice, the artery reassembly after myocardial infarction could be triggered by administering a single dose of CXCL12." (PMID 35391845, 2022). "Furthermore, myocardial infarct size following an ischemic episode has been reduced by the injection of CXCL12." (PMID 36247468, 2022). "This indicates that the early administration of exogenous CXCL12 may improve cardiac function after myocardial infarction." (PMID 35668739, 2021). "CXCL12 is a powerful angiogenic factor that recruits endothelial progenitor cells from the bone marrow and have regenerative and tissue protective effects in ischemic conditions, such as myocardial infarction." (PMID 28638723, 2017). "In a mouse model of myocardial ischemia, CXCL12 treatment leads to increased levels of vascular endothelial growth factor (VEGF) and enhanced neo-angiogenesis, associated with reduced infarction size after myocardial infarction." (PMID 26347749, 2015).
myocardial infarction (continued). "Interestingly, recent genome-wide association studies (GWAS) revealed CXCL12 as an important candidate gene associated with CAD and myocardial infarction (MI), but the underlying mechanisms remain totally unclear." (PMID 24966838, 2014). "Also, the transplantation of CXCL12-overexpressing endothelial progenitor cells during myocardial infarction in rats could increase neo-angiogenesis." (PMID 26347749, 2015). "Furthermore, inhibition of the CXCL12/CXCR4 axis can improve cardiac fibrosis and promote tissue repair after myocardial infarction." (PMID 35668739, 2021). "SDF-1, a small chemoattractive cytokine designated as chemokine (C-X-C motif) ligand 12 (CXCL12), was up-regulated immediately after myocardial infarction and could sufficiently induce the migration of MSCs to injured sites." (PMID 23834470, 2013). "It is suggested that CXCL12/CXCR4 interaction is important, especially in the injury-related stem cell recruitment after myocardial infarction, whereas CXCL12 action alone seems to be insufficient for mobilization of CXCR4 expressing cells in physiological situations." (PMID 18298660, 2008). "Finally, GXDS, when administered orally, in combination with MSC transplantation, may improve acute myocardial infarction by reducing apoptosis at the site of injury, generating new blood vessels, and promoting MSC migration by increasing CXCL12 expression." (PMID 32582713, 2020). "However, we showed here that both CXCL12 and β3-AR signalling are needed, and neither is sufficient for the pharmacological enhancement of myocardial infarction-induced MSC mobilisation, as mirabegron only or AMD3100 only did not result in significant increase of circulating MSCs." (PMID 36263604, 2023). "Summing up, heparin might exert beneficial effects on atherosclerotic lesion formation by blocking CXCL12 and CXCL4, but the induction of atherogenic leukocytosis might counter-balance these positive effects and additionally impede healing processes after myocardial infarction." (PMID 25152735, 2014).
atherosclerosis (93 papers, 2012 to 2026). A disease characterized by the build-up of fatty material and calcium deposition in the arterial wall resulting in partial or complete occlusion of the arterial lumen. "This established a significant association between ABCA1 and CXCL12 gene expressions with atherosclerosis, partly influenced by HIV." (PMID 39483879, 2024). "A previous study showed that blocking the CXCL12/CXCR4 chemokine receptor axis in mice can accelerate the process of atherosclerosis by causing an increase in the number of neutrophils in peripheral blood and plaques." (PMID 39759498, 2024). "Previously, we established that endothelial cell-derived inflammatory chemokine CXCL12 drives atherosclerosis as its deficiency decreased lesion sizes in the aortas of hyperlipidemic mice." (PMID 35674847, 2022). "Another key discovery is the association between the CXCL12 hubgene and the development of atherosclerosis." (PMID 36247468, 2022). "Reduced aortic lesions were observed in mice with arterial endothelial (EC)-specific CXCL12 deficiency, suggesting that CXCL12 from ECs can promote atherosclerosis." (PMID 35668739, 2021). "A recent study by Döring and colleagues dissected the role of CXCL12 in atherosclerosis by establishing a comprehensive cell-specific deficiency of the chemokine in ApoE−/− mice." (PMID 33503867, 2021). "In a rat model of diabetes, a metabolic disorder associated with a higher prevalence of atherosclerosis, high glucose levels were shown to trigger activation, proliferation, and enhanced chemotaxis of VSMCs via stimulation of the CXCL12/CXCR4 axis." (PMID 24966838, 2014). "The C-X-C motif chemokine ligand 12 (CXCL12) gene has been implicated in atherosclerosis; however, its relationship with lipoprotein subfraction profiles remains unclear." (PMID 42279066, 2026). "However, until now there have been no studies directly investigating the causal cell-type-specific effects of CXCL12/CXCR4 in relation to atherosclerosis." (PMID 26257740, 2015). "However, already various studies have showed clear associations of cell-type-specific expression of CXCL12 with atherosclerosis development." (PMID 26175090, 2015). "CXCL12 is a secreted protein secreted by the stromal cells including endothelial cells and plays a role in promoting atherosclerosis by intensifying multiple pathogenesis of atherosclerosis, including inflammation, dyslipidemia and so on." (PMID 39763069, 2025). "Taken together, the activation of the MAPK6‒TRIM21 ubiquitin‒proteasome complex in ECs following DSS stimulation promotes atherosclerosis by regulating endothelial inflammation through the EGR1/CXCL12 axis." (PMID 39763069, 2025). "CXCL12 derived from endothelial cells affects the progression of atherosclerosis, and the source of its release has a crucial impact on its role in vascular inflammation." (PMID 40535169, 2025). "AAV‐MAPK6, ApoE−/−MAPK6flox/floxTEKCre mice and the CXCL12 neutraligand were used to confirm the beneficial effects of MAPK6 against atherosclerosis." (PMID 39763069, 2025). "In the next phase of our research, we plan to investigate the role of the miR166a-3p/CXCL12 pathway in atherosclerosis by overexpressing or knocking out the CXCL12 gene in transgenic mice." (PMID 38475787, 2024). "We also elucidated a cluster of chemokine signaling regulation via microRNAs involving CXCL12 and CXCR4 (miR-126-5p/-3p, miR-146a-5p/-3p and miR-494-5p)—factors closely associated with atherosclerosis development and progression." (PMID 39337512, 2024). "For example, atherosclerosis can induce the expression of Vcam-1, Icam-1, Cxcl12, and Cx3cl1 in SMCs, which in turn facilitates binding to monocytes." (PMID 37686377, 2023). "We reported recently that MF-specific IGF-1 overexpression decreases CXCL12 plaque and circulating levels and promotes atherosclerosis in mice." (PMID 36602878, 2023).
atherosclerosis (continued). "In cardiovascular disease, it has been shown that CXCL12 is proatherogenic in the development and progression of atherosclerosis." (PMID 37207221, 2023). "Considering the substantial evidence suggesting CXCL12 had a preventive function in atherosclerosis when Apoe−/− mice were given intravenous CXCL12." (PMID 37928902, 2023). "In our opinion, the results we obtained indicate the important role of the CXCL12/CXCR4/CXCR7 axis in the development of atherosclerosis." (PMID 36077592, 2022). "CXCL12 promotes atherosclerosis by deregulating the cholesterol metabolism of macrophage foam cells and leads to the acceleration of atherosclerosis." (PMID 36670934, 2022). "We further evaluate the role of ACKR3 in the hematopoietic compartment due to the importance of the contribution of immune cells to atherosclerosis as well as the important regulatory roles of CXCL12 in the hematopoietic cell compartment." (PMID 35674847, 2022). "Combined, these observations suggest that EC-derived CXCL12 promotes atherosclerosis and vascular remodeling." (PMID 35600479, 2022). "Showing the predominant effect of CXCL12/CXCR4/ACKR3 axis in different cells involved in atherosclerosis." (PMID 34494495, 2021). "CXCL12 is a member of the chemokine family exerting a myriad role in atherosclerosis through its classical CXCR4 and atypical ACKR3 (CXCR7) receptors." (PMID 34494495, 2021). "It is also interesting to note that during atherosclerosis, EC-derived apoptotic bodies are formed, which trigger the production of CXCL12 through microRNA-126, consequently trigger the recruitment of progenitor cells, and lead to plaque stability." (PMID 34494495, 2021). "The modulatory and regulatory functional spectrum of CXCL12/CXCR4/ACKR3 axis in atherosclerosis spans from proatherogenic, prothrombotic and proinflammatory to atheroprotective, plaque stabilizer and dyslipidemia rectifier." (PMID 34494495, 2021). "For a clearer picture of the association between EC CXCL12/CXCR4 and atherosclerosis, five different models of CXCL12-knockout were created, and the lesion area, macrophage content and collagen content were studied." (PMID 34494495, 2021). "This outcome was observed along with a systemic decrease of circulating CXCL12 levels leading to the conclusion that EC-derived CXCL12 promotes atherosclerosis." (PMID 33503867, 2021). "In recent years, it has been found that CXCL12 is closely related to the formation and stability of atherosclerosis plaque, and also plays an important role in angiogenesis, thrombosis and intimal hyperplasia in atherosclerotic lesions." (PMID 33880887, 2021). "The role of CXCL12 in atherosclerosis is controversial, although there is substantial evidence indicating that CXCL12 plays a protective role." (PMID 35668739, 2021). "Its role and its endogenous ligand C-X-C motif chemokine 12 (CXCL12) in atherosclerosis is yet to be fully elucidated." (PMID 34685553, 2021). "Some clinical observations confirm that the role of CXCL12 per se is proatherogenic in atherosclerosis development and progression." (PMID 34987703, 2021). "The CXCL12/CXCR4/ACKR3 axis performs distinct functions in the pathophysiology of atherosclerosis, ranging from atheroprotective to proatherogenic functions across various cell types, through its receptors CXCR4 and ACKR3." (PMID 34494495, 2021). "The lesions improved in EC-knockout models specifically, along with a decrease in the level of circulating CXCL12, suggesting that EC-derived CXCL12 promotes atherosclerosis." (PMID 34494495, 2021). "Combination of CXCL4 and CCL5 was shown to exacerbate disease in a mouse model of atherosclerosis, and CXCL12 in combination with HMGB1 enhanced monocyte recruitment in a mouse model of tissue damage." (PMID 33123134, 2020). "Upregulation of RGS1 in peripheral blood T lymphocytes decreased their chemotactic response to CXCL12 and CCL19, both implicated in atherosclerosis." (PMID 32443695, 2020).
atherosclerosis (continued). "Administration of ApoBDs carrying miR-126 inhibits atherosclerosis and induces CXCL12-dependent vascular protection." (PMID 33134295, 2020). "CXCL12 silencing resulted in a significant 42% reduction in adventitial lymph vessel density, underpinning the causal role that CXCR4/CXCL12 plays in atherosclerosis associated lymph vessel expansion." (PMID 28349940, 2017). "Conversely, CXCL12 expression can be induced by miR-126 in ECs through an auto-amplifying feedback loop to facilitate endothelial regeneration, thus limiting atherosclerosis and mediating plaque stabilization." (PMID 26001902, 2015). "In recent years, more research has focused on determining the role of CXCL12 in atherosclerosis development." (PMID 26175090, 2015). "Various human studies supported the idea that CXCL12 is a potential regulatory agent in atherosclerosis." (PMID 26257740, 2015). "The upregulation of endothelial CXCL12 mediated by apoptotic body-derived miR-126-3p in early atherosclerosis reduces lesion formation by diminishing the lesional macrophage content and increasing SMC content in a CXCR4-dependent process." (PMID 26001902, 2015). "The alternative receptor for CXCL12 and CXCR7 has also been implicated in atherosclerosis development, as activation of this receptor reduced lesion formation, by increasing the VLDL uptake in adipose tissue." (PMID 26175090, 2015). "Although there are still some contradictory clinical results, it is clear that CXCL12 does play a role in atherosclerosis and CVD." (PMID 26257740, 2015). "Subsequently, the role of two important inflammatory mediators that recently have been connected with CVD and atherosclerosis will be discussed and put into clinical perspective, namely the chemokines CXCL12 and macrophage migration-inhibitory factor (MIF)." (PMID 26257740, 2015). "A recent study showed that injections of CXCL12 in mice developing atherosclerosis resulted in more stable lesions, characterized by more SMCs and a thicker fibrous cap." (PMID 26257740, 2015). "Together, these results show that CXCL12/CXCR4 have interactions with many cells that are relevant in atherosclerosis and is thereby modulating atherosclerosis development." (PMID 26257740, 2015). "In contrast, the role of the CXCL12/CXCR4 axis in native atherosclerosis remains largely unclear, with mostly only in vitro studies shedding some light on the effect of CXCR4 signaling on cell type-specific functions relevant in atherogenesis." (PMID 24966838, 2014). "This suggests potential different roles of CXCR4 and its ligand CXCL12 in atherosclerosis through interplay of CXCR4 with MIF." (PMID 24966838, 2014). "CXCL12 is a common chemokine that can attract most cells including T lymphocytes and its level is increased in atherosclerosis lesions." (PMID 24743945, 2014). "These endothelial cell-derived apoptotic bodies trigger, via miR-126, the production of CXC chemokine CXCL12 in the recipient vascular cells which limits atherosclerosis and confers plaque stability." (PMID 24273550, 2013). "The first study presented evidence that endothelial cell-derived apoptotic bodies are generated during atherosclerosis and lead to the induction of the expression of CXCL12 in recipient endothelial cells." (PMID 24273550, 2013). "The serum CXCL12 concentration is also closely related to atherosclerosis." (PMID 39763069, 2025). "However, the role of the CXCL12/CXCR4/ACKR3 axis in atherosclerosis includes a large range of cell-type-specific biological effects." (PMID 40986007, 2025). "In detail, the decrease in MAPK6 expression promotes the interaction between EGR1 and NF‐κB and ultimately accelerates the accumulation of NF‐κB in the nucleus, which promotes the transcription of CXCL12, thereby accelerating the progression of atherosclerosis." (PMID 39763069, 2025).